SLC22A10 (solute carrier family 22 member 10 (gene/pseudogene))
Synonyms: OAT5; hOAT5
Tractability: Small molecule: it belongs to a druggable protein family. Antibody: UniProt predicts a signal peptide or a membrane-spanning region.
Gene: Protein-coding gene on chromosome 11 (63,268,022 to 63,311,874, forward strand). Ensembl gene ENSG00000184999.
Subcellular location: Membrane
Gene Ontology:
Molecular function: transmembrane transporter activity
Biological process: transmembrane transport
Cellular component: membrane
Genetic constraint (gnomAD): Loss-of-function variants: 47 observed, 44.85 expected, observed/expected ratio (o/e) 1.05, 90% interval 0.83 to 1.34. The upper end of that interval is the gene's LOEUF score, 1.34, which puts it in group 5 of 6, group 1 being the genes least tolerant of losing a copy. Missense variants: 687 observed, 620.72 expected, observed/expected ratio (o/e) 1.11, 90% interval 1.04 to 1.18. Synonymous variants: 248 observed, 221.3 expected, observed/expected ratio (o/e) 1.12, 90% interval 1.01 to 1.25.
Homologues: Orthologues: chimpanzee SLC22A10 (99% identical), dog SLC22A10 (67% identical), zebrafish oatx (41% identical), zebrafish si:dkey-166k12.1 (31% identical), zebrafish slc22a4 (28% identical), Drosophila melanogaster Orct2 (27% identical), Drosophila melanogaster Orct (27% identical), Caenorhabditis elegans oct-2 (27% identical), Caenorhabditis elegans oct-1 (26% identical), zebrafish si:dkey-119m7.4 (26% identical), Drosophila melanogaster CG42269 (25% identical), Drosophila melanogaster CG6356 (24% identical), and 41 more. Paralogues in human: SLC22A24 (60% identical), SLC22A25 (60% identical), SLC22A9 (57% identical), SLC22A12 (49% identical), SLC22A11 (48% identical), SLC22A6 (38% identical), SLC22A8 (38% identical), SLC22A7 (31% identical), SLC22A13 (29% identical), SLC22A3 (29% identical), SLC22A5 (27% identical), SLC22A2 (26% identical), and 10 more.
Diseases named in the same sentence as SLC22A10 in open-access papers:
SLC22A10 is named in the same sentence as 8 diseases in open-access papers, as found by Europe PMC text mining. Sharing a sentence is not in itself a finding about the gene and the disease. The quoted sentences say what the papers report.
breast carcinoma (2 papers, 2021 to 2022). "Of these twenty, three showed evidence of association with LoF variants for overall breast cancer (ZFAND1, TYRO3, TMEM206/PACC1), and a further six with breast cancer subtypes (DNAH11, PARP2, LAMC3, MTMR11, EPN3, SLC22A10)." (PMID 35884425, 2022). "Analysis of rare missense variants identified evidence of associations of TMEM161A, SIPA1L1, and ERCC2 with overall breast cancer, RNF175 and NCKAP1L with ER-positive disease, and SLC22A10, PHAX, SMARCA2, EML5, NTRK3, and MED23 with ER-negative disease." (PMID 35884425, 2022). "We found nominal evidence of association with breast cancer overall for LoF variants in three genes (ZFAND1, TMEM206/PACC1, and TYRO3), with ER-negative breast cancer in two genes, DNAH11 and PARP2, and with ER-positive disease in four genes LAMC3, MTMR11, EPN3, and SLC22A10." (PMID 35884425, 2022).
dementia (1 paper, 2022). Loss of intellectual abilities interfering with an individual's social and occupational functions. "The results suggest that rare variants in IFFO1, DTNB, NLRC3, and SLC22A10 heighten susceptibility to neuronal injury and inflammation, potentially by altering cytoskeleton structure and immune activity disinhibition, resulting in an elevated dementia risk." (PMID 35173266, 2022).
endometriosis (1 paper, 2022). The growth of functional endometrial tissue in anatomic sites outside the uterine body. "We established the involvement in the endometriosis biology of SNP rs112295236 SLC22A10 within three multi-tiered (2,3,4 loci) most worthwhile intergenic epistatic models." (PMID 36430184, 2022).
kidney disease (1 paper, 2019). "Studies on SLC22A10 were mainly on kidney disease, especially on the nephrotoxicity of the drugs." (PMID 30755830, 2019).
SLC22A10 also shares sentences with these, for which no sentence is quoted: tumor (2 papers); Alzheimer disease (1); calcification (1); renal failure (1).